MAGEB3 (MAGE family member B3)
Synonyms: CT3.5
Tractability: PROTAC: ubiquitination databases record sites on it.
Gene: Protein-coding gene on chromosome X (30,230,657 to 30,237,495, forward strand). Ensembl gene ENSG00000198798.
Gene Ontology:
Molecular function: protein binding
Biological process: negative regulation of transcription by RNA polymerase II
Cellular component: nucleus; cytoplasm
Homologues: Orthologues: macaque MAGEB3 (93% identical), pig MAGEB3 (69% identical), rabbit MAGEB3 (63% identical), rat Mageb3 (58% identical), zebrafish ndnl2 (24% identical), Drosophila melanogaster MAGE (18% identical). Paralogues in human: MAGEB4 (54% identical), MAGEB1 (51% identical), MAGEB18 (49% identical), MAGEB17 (47% identical), MAGEB2 (47% identical), MAGEB10 (46% identical), MAGEB16 (43% identical), MAGEB6 (42% identical), MAGEB6B (42% identical), MAGEA10 (41% identical), MAGEB5 (40% identical), MAGEA11 (39% identical), and 25 more.
Diseases named in the same sentence as MAGEB3 in open-access papers:
MAGEB3 is named in the same sentence as 6 diseases in open-access papers, as found by Europe PMC text mining. Sharing a sentence is not in itself a finding about the gene and the disease.
MAGEB3 shares sentences with these, for which no sentence is quoted: colon cancer (1 paper); colorectal cancer (1); liver cancer (1); lymph node metastasis (1); melanoma (1); tumor (1).